IFNG (interferon gamma)
Diseases named in the same sentence as IFNG in open-access papers (continued):
Sharing a sentence is not in itself a finding about the gene and the disease.
tumor (continued). "Taken together, the treatment with IFNα facilitated the activation of γδ T cells to produce IFNγ, which might be therapeutically interesting in clinical settings in which tumor-triggered αβ T cells play an important role." (PMID 37139603, 2023). "We then assembled a panel of genes associated with cancer immunity and immune evasion mechanisms including checkpoint molecules, antigen processing and presentation genes, specific chemokines and cytokines, and tumor cell-specific interferon γ (IFNγ)-related genes." (PMID 38047086, 2023). "After validating that IFNγR1−/− B16Nectin1 cells were truly insensitive to IFNγ-mediated effects, we challenged wild-type mice with either control or IFNγR1−/− tumor cells, established palpable tumors, and began treatment with dual checkpoint blockade or IL-12 virotherapy." (PMID 36881506, 2023). "HRD-EXCUTE could further induce the interferon phenotype including the expression of IFNG and PD-1/PD-L1 and the infiltration of immune cells into tumor microenvironment." (PMID 37063431, 2023). "Furthermore, to target also the fibroblast growth factor receptor (FGFR) with lenvatinib has demonstrated additional anticancer activity by restoring the tumor response to IFNγ stimulation in a current preclinical study." (PMID 37740836, 2023). "More precisely, in growing tumours, DCs and cancer cells secrete IFNβ, while T cells produce IFNγ." (PMID 36817445, 2023). "The present study suggests the importance of the IFNγ pathway in ICI therapy, and further studies could identify potential strategies to enhance ICI treatment by inhibiting the pro-tumor effects of IFNγ and inducing its anti-tumor effects." (PMID 38026978, 2023). "For example, after successfully removing the tumor by surgery, many patients still developed distant metastasis later; one of the important reasons is that low NK cell cytotoxicity and less IFNγ secretion link impaired NK cell function directly to increased postoperative metastases." (PMID 37190251, 2023). "However, several lines of evidence also point to IFNγ as a factor restricting antitumor immunity by promoting tumor initiation, growth and immune evasion." (PMID 36658158, 2023). "Efficient tumor control correlated with the induction of high frequencies of neoepitope-reactive T cells measured by the presence of T cells that simultaneously produce TNFα and IFNγ upon neopeptide re-stimulation." (PMID 37720215, 2023). "However, oncogenic or inflammatory cytokines have been shown to activate PDL1 expression in the tumour, especially interferon-gamma." (PMID 37760608, 2023). "The reason for this partial resistance to DuoBody-CD3x5T4–induced tumor cell kill is not fully understood but might involve differential sensitivity of the tumor cells to Fas or IFNγ signaling." (PMID 36271507, 2022). "This increase in exosomal PD-L1 during PD1-inhibitor treatment may be an adaptive response of tumor cells to T-cell regeneration through interferon-gamma production by reinvigorated CD8+ T cells." (PMID 36428710, 2022). "Thus, the augmented tumor-infiltrated cytotoxic CD8+IFNγ+GZM-B+ T cell content is more due to decreased infiltration of G-MDSCs." (PMID 35332119, 2022). "A lack of this urothelium-specific IFNγ-signature was associated with increased risk of progression in T1 tumours and decreased overall survival in the basal/squamous sub-type of MIBC." (PMID 36358715, 2022). "Here, we analyse the molecular mechanisms involved in silencing TFF1, one of the protective and tumour-suppressing genes, in the context of the chronic inflammation triggered by H. pylori infection, focusing on the role of IFNγ, one of the major cytokines expressed during this inflammatory response." (PMID 36514982, 2022). "Moreover, IFNγ production by tumor-specific CD8+ T-cells in response to melanocytic antigens has been shown to be impeded via BTLA signaling." (PMID 36291815, 2022).
tumor (continued). "However, in heterogeneous tumors in which wildtype tumor cells were admixed with STUB1-deficient cells, STUB1 deficiency strengthened IFNγ signaling, thereby enhancing the response to anti-PD-1 treatment." (PMID 35395848, 2022). "Furthermore, IL-12 plus GM-CSF-treated tumor-bearing mice induce long-term maintenance of IDO+ DC in the tumor-draining LNs (TDLNs) through transient induction of IFNγ." (PMID 36244976, 2022). "Similarly, adoptively transferred CD4+ T cells specific for an MHC-II-restricted, tumor-specific peptide were found to eliminate MHC-II-negative UV-induced fibrosarcoma 6132A-PRO tumors by an indirect mechanism dependent on IFNγ activation of host cells." (PMID 36159781, 2022). "It has been found that in some cases, IFNG obviously plays a role in inducing tumor progression, and its induced PD-L1 expression could serve as a novel mechanism by which it impairs tumor immunity." (PMID 35265525, 2022). "Importantly, tumour-associated T cells had improved IFNγ production, indicating that VSV pretreatment was capable of increasing the functional capacity of T cells and controlling tumour growth." (PMID 35205725, 2022). "The antagonism relationship between interferon signaling in cancer cells and immune cells might be the reason explaining the contradictory roles of IFNG in tumor immune response." (PMID 35692844, 2022). "Likewise, in mice bearing orthotopic KRasG12D pancreatic intra-epithelial neoplastic lesions, Tirabrutinib administration decreased stromal accumulation of regulatory B cells in favour of CD8+IFNγ+ cytotoxic T cells, and decreased tumor growth." (PMID 36175961, 2022). "Moreover, ex vivo stimulation of lung-resident CD8 + TRMs with anti-PD-1 enhances their IFNγ secretion and their capacity to kill autologous tumor cells." (PMID 34743182, 2022). "Additionally, intracellular cytokine staining in YUMM3.3 tumor-infiltrating CTLs revealed a marked INHBA-induced decrease in IFNγ, TNFα, and GzmB protein levels." (PMID 35580932, 2022). "This dual blockade upregulated PD-L1 expression in tumor endothelial cells through IFNγ." (PMID 36140392, 2022). "Taken together, we propose a framework whereby STUB1 may confer ICB resistance by downregulating IFNGR1 on the cell surface, thus curbing the tumour cells’ ability to sense and respond to IFNγ." (PMID 35982220, 2022). "In other tumor models, CD4+ T cell-derived IFNγ could inhibit tumor angiogenesis by acting directly on tumor cells, which requires tumor responsiveness to IFNγ." (PMID 36159781, 2022). "We also assessed whether the levels of RANTES, TNFα, IFNγ, TGF- β1, PD-L1, VEGF-A, and VEGF-C were associated with some histopathological parameters: MVD (microvessel density), budding, and tumor-infiltrating lymphocytes." (PMID 35208526, 2022). "It has been proposed that IFNγ induce PD-L1 expression as an immune evasion mechanism by the tumor." (PMID 35924147, 2022). "In a fibrosarcoma mice model, administration of anti-CTLA-4 anti-body caused raised levels of the IFN-inducible enzyme 2′,5′-oligoadenylate synthetase (OAS), a positive regulator of anti-tumor response, in draining lymph nodes concurrent with augmented levels of IFNγ in tumor lysates." (PMID 35392976, 2022). "It has been evidenced that type II IFN (also known as IFNγ) could suppress tumor growth by affecting immune cells and tumor cells." (PMID 36323801, 2022). "We also observed increases in the percentages of tumor-infiltrating lymphocytes (TIL) producing IFNγ and activation marker Granzyme B (GZMB), and a reduced fraction of FOXP3+ T regulatory cells, whereas the fraction of CD11b+ Ly6G+ neutrophils and F4/80+ CD11b+ macrophages remained constant." (PMID 35915084, 2022). "In this tumor context, the activation of the immune system will lead to the secretion of anti-cancer cytokines, such as Interferon-gamma (INF-γ), TNF-α, and IL-6, and cell phagocytosis to eliminate the tumor, thus becoming a tool for the development of new treatments in cancer therapy." (PMID 36011024, 2022).
tumor (continued). "Pretreating A375 cells overexpressing B3GNT2 with either kifunensine or BAG showed that these ten ligands and receptors are primarily N-glycosylated, aligning with our finding that kifunensine treatment had a stronger effect on T cell IFNγ secretion and tumor cell survival." (PMID 35338135, 2022). "Intriguingly, PZH could suppress the IFNγ triggered tumor cell resistance via downregulating PD-L1 expression, which improves the opportunity for PZH inhibited CRC immune escape." (PMID 35185580, 2022). "It is plausible that the PD-1 blockade induced conversion of CD25+Foxp3+ CD4 Tregs into CD25−Foxp3+ CD4 Tregs38, since we observed the intratumoral transferred CD25+Tregs with PD-1 blockade had decreased tumor egress, along with increased conversion to IFNγ-producing CD25-Tregs." (PMID 35449134, 2022). "When the balance shifts to ferroptosis-mediated immunosuppression, the ferroptosis of tumor cells induced by IFNG may weaken anti-tumor immunity and even lead to acquired tolerance to immunotherapy." (PMID 35692844, 2022). "Infiltrating T cells secrete more IFNγ, which stimulate tumor cells via JAK-STAT signaling to overexpress PD-L1, as well as many other known and unknown molecules, to inhibit T cell function." (PMID 35440133, 2022). "In addition, antigen-specific CD4+ T cells showing a Th1 IFNγ-producing phenotype were detected against tumor growth; this was identified recently as an additional mechanism for controlling tumor growth." (PMID 35217706, 2022). "IFNγ-mediated suppression of SLC7A11 results in enhanced tumor lipid oxidation and ferroptosis." (PMID 36003368, 2022). "PD-L1 (programmed death-ligand 1) expression is found to be elevated on tumour cells following irradiation due to interferon gamma (IFN-γ) release from tumour-infiltrating lymphocytes (TILs) and TILs have increased expression of PD-1 (programmed death-1) following ex-vivo irradiation." (PMID 36106115, 2022). "IFNG (interferon gamma) plays an important role in tumor immunotherapy." (PMID 35719954, 2022). "Furthermore, IFNγ has the ability to upregulate immune checkpoint ligands, inducing tumor cell dormancy, apoptosis, and hyperplasia." (PMID 35582541, 2022). "Firstly, other markers of relevance including the genomic profile, tumor mutational burden, and the inflammatory factor interferon-gamma were not evaluated." (PMID 35720388, 2022). "Therefore, it is likely that p40 mAb is also increasing the level of IFNγ in TNBC tumor of PDX mice via stimulation of IL-12Rβ1 internalization and upregulation of the IL-12 signaling pathways." (PMID 35053375, 2022). "Importantly, Vγ2 x PD-L1 induced efficient tumor cell lysis, and IFNγ secretion was observed at an E: T ratio as low as 0.3125:1 for these three cell lines." (PMID 35784353, 2022). "The results suggest that the anti-tumor mechanism mediated by αCTLA-4 treatment in the IM vaccination may skew the neoantigen-specific immune response toward a CD8+IFNγ+ effector function whereas in the ID vaccination in the direction of CD4+TNFα+." (PMID 35110563, 2022). "Furthermore, as tumor growth progresses, both mouse and human NK cells exhibit decreased expression of the degranulation marker CD107a, as well as decreased IFNγ and perforin." (PMID 35844626, 2022). "Hence, increasing IFNγ in the tumor site can be considered a promising strategy to restore CAR T cell-tumor cell interaction through ICAM-1 upregulation." (PMID 35681548, 2022). "For example, IFNG and genes encoding cytolytic enzymes (GZMA, GZMB and PRF1) were relatively up-regulated in SCLC-I tumors, indicating that SCLC-I tumors are characterized by a high level of tumor-infiltrating lymphocytes with potential cytolytic activity." (PMID 36428693, 2022). "However, corylin inhibited the mRNA expression and protein levels of Ifnγ, Tnf-α, Il-6, Il-1β, Nlrp3, Asc, Pannexin, and Pro-caspase 1 in the tumor tissues of AOM/DSS-induced CAC mice." (PMID 35269806, 2022).
tumor (continued). "In summary, the dynamic and kinetic impact of IFNγ on immunogenicity and immune evasion may determine the fate of tumor progression." (PMID 34385592, 2022). "This bsApt also induced an immune response (infiltration of CD3+ lymphocytes at tumor with increased expression of IFNγ, TNFα, and IL-10) and potentiated a combination of GVAX and transient Foxp3 blockade via the P60 peptide (resulting in decreased tumor size and increase survival) in vivo." (PMID 35141049, 2022). "Even though IFNγ signaling and PD-L1 have been tightly linked, our data and those of others demonstrate that IFNγ induces an intrinsic effect in tumor cells that is independent of PD-L1 expression." (PMID 35656514, 2022). "PD-1/PD-L1 blocking antibody indeed elevates the effector function of CD8+ T cells in the short term, while activated effector T cells release a large amount of IFNγ to kill tumor cells, leading tumor cells to evade the surveillance of immune system through the inherent resistance mechanisms." (PMID 35185580, 2022). "IFNγ is involved in regulating tumor cell proliferation and apoptosis." (PMID 35799605, 2022). "In addition, ablation of the nuclear factor κB subunit c-Rel increases IFNγ expression in Tregs, thereby delaying tumor growth." (PMID 34385592, 2022). "However, the frequency of IFNγ+CD8+ T cells was again increased within the tumor-draining lymph nodes of B16F10 tumor-bearing mice." (PMID 36923556, 2022). "Interferon-gamma has been shown to protect against tumor development." (PMID 35853961, 2022). "Moreover, the combo gel treatment also significantly stimulated programmed death-ligand 1 (PD-L1) upregulation on tumor cells, consistent with the enhanced expression potential of IFNγ by CD8+ and CD4+ TILs." (PMID 35780226, 2022). "Whether the IFNγ-JAK-STAT1-p16Ink4a axis was involved in tumor cell senescence induced by dual inhibition of H3K9me2 and H3K27me3 remains to be explored." (PMID 35409271, 2022). "Meanwhile, the IFNγ secretion by tumor-resident effector T cells after BSA-Man@Mn2+-Ft@Lap administration increased by about 17% comparing to PBS group, immediately suggesting the nanoassembly-induced promotion of effector T cell activation and infiltration into tumor tissues." (PMID 36167857, 2022). "However, prolonged IFNγ exposure can promote pro-tumorigenic effects (checkpoint activation, angiogenesis, and tumor cell proliferation)." (PMID 36551577, 2022). "In addition, we selected cisplatin because it is widely used to treat MPM patients and because in our in vitro co-culture system, we found that pretreatment of AB12 cells with cisplatin stimulated the production of IFNg by anti-tumor splenocytes." (PMID 36685577, 2022). "On the one hand, IFNG involves in the differentiation of Th1 cells, maintains the Th1-type immune response, as well as enhances the cytotoxicity of T lymphocytes, making the IFNG gene signatures effective biomarkers of an activated anti-tumor immune response." (PMID 35492352, 2022). "A later study by the same group found that rejection of different tumors that are primarily controlled by CD8+ T cells was correlated with inhibition of tumor-induced angiogenesis likely via an IFNγ-dependent mechanism, suggesting a shared mechanism for tumor rejection by both CD4+ and CD8+ T cells." (PMID 36159781, 2022). "Finally, upon exposure to a combination of IFNγ and TNFα, loss of STUB1 further sensitized tumour cells to growth inhibition in vitro." (PMID 35982220, 2022). "First, CAR T cells get activated at the periphery of tumor islets and start producing IFNγ." (PMID 36189315, 2022). "However, IFNγ signal can also induce tumor ischemia and homeostasis program, and the result is tumor clearance or tumor escape." (PMID 35069712, 2022).
tumor (continued). "IFNG increases tumour cell immunogenicity, by upregulating components of the major histocompatibility complex (MHC) class I protein and promotes maturation of dendritic cells (DCs), generation of Th1 cells and CTLs and activates cytocidal activity in macrophages." (PMID 35445563, 2022). "Clinical trial studies are now emerging based on the therapeutic inhibition of the histone methyltransferase EZH2, a key epigenetic regulator found to suppress the immunogenicity of tumour cells via transcriptional repression of genes involved in IFNγ response and antigen presentation." (PMID 35327375, 2022). "But an interesting phenomenon was that IFNG could promoted T cell exhaustion via the PDL1 pathway in the tumor immune process." (PMID 35692844, 2022). "While the role of IFNγ in cancer is still controversial, this cytokine could exploit both anti-tumor and pro-tumor activities as well." (PMID 36405727, 2022). "Moreover, systemic expression of IL-12+IL-18 leads to a prevalence of TVM cells expressing IFNγ in tumors and defines these cells as an essential factor for tumor growth control in the early stages of disease." (PMID 36330506, 2022). "Interferon gamma (IFNγ) is a pleiotropic cytokine that is a key regulator of anti-tumor immunity." (PMID 35902886, 2022). "IFNγ has demonstrated pro-apoptotic effects through induction of ROS and nitric oxide, though tumor cells are not universally susceptible to IFNγ-mediated cell death." (PMID 35592329, 2022). "The increased abundance of IFNγ secreting CD4+ TILs in CaMKK2-deficient mice, in addition to chemotactic signals from DC-like TAMs (Cxcl9, Cxcl10), may explain the enhanced tumor penetrance seen by CD4+ and myeloid cells in the setting of CaMKK2 deficiency." (PMID 36309495, 2022). "In the group of SFRT, they observed the abscopal immune response in contralateral tumors with obviously increased infiltration of both antigen-presenting cells and activated T cells, followed by an increase in systemic IFNγ production and ultimately a delay in tumor growth." (PMID 36713375, 2022). "However, also PD-L1 represents an established IFNγ target, which we confirm here, and this constitutes an immune-protective tumor trait." (PMID 35395848, 2022). "Notably, both Kaede Green+ and Kaede Red+ CD8 T cells in the tumor showed a significant increase in the proportion expressing Granzyme B and IFNγ." (PMID 35472220, 2022). "Proteins associated with tumor regression including granzyme A (GZMA) and Th1 markers such as the C-X-C motif chemokine ligand family (CXCL9, CXCL10, CXCL11) and interferon gamma (IFNG) mirrored the checkpoint inhibitor decreases seen in tissue during single agent pembrolizumab therapy." (PMID 36572780, 2022). "Interferon-gamma (IFNG) is essential for immune and tumor control of intracellular pathogens." (PMID 36506032, 2022). "Luminex-based multi-cytokine analysis in the peripheral blood of tumor-bearing mice on day 35 demonstrated elevated levels of inflammatory cytokines (IFNγ, IL-1β, TNFα and Il-17) in the HS diet cohort, while there were elevated anti-inflammatory IL-10 blood levels in the LS diet cohort." (PMID 35741331, 2022). "Interestingly, we found that the addition of the anti-PD-L1, -PD-1 or LAG-3 mAb to the tribody significantly increased the tumor cells lysis accordingly to the higher secretion of IFNγ cytokine, detected after treatments." (PMID 36071464, 2022). "The accumulation of IFNγ+ CD8+ T cells is significantly impaired in MHC-Ia-deficient mice, indicating that the 11-strain mixture promoted a killing effect of tumor antigen-specific CD8+ T cells through MHC-I+DC-mediated cross-presentation of tumor antigens." (PMID 35355998, 2022). "In the context of CTL attack, IFNγ was shown to sensitize tumor cells to ferroptosis by down-regulating the expression of SLC3A2 and SLC7A11, key regulators of cysteine homeostasis whose inhibition in turn leads to disrupted cysteine uptake and lipid peroxidation." (PMID 35592329, 2022).